BMAL1 (basic helix-loop-helix ARNT like 1)
Diseases named in the same sentence as BMAL1 in open-access papers (continued):
Sharing a sentence is not in itself a finding about the gene and the disease.
periodontitis (8 papers, 2022 to 2025). An acute or chronic inflammatory process that affects the tissues that surround and support the teeth. "Bone loss was prominent in the Bmal1- periodontitis group; the range of resorption was significantly larger compared with that in the wild-type periodontitis group, and the alveolar crest was destroyed." (PMID 40008712, 2025). "Similarly, bone loss in the wild-type (Bmal1+/+) periodontitis group was significantly more severe than in the uninfected wild-type (Bmal1+/+) group (p<0.001)." (PMID 40008712, 2025). "Our study found that BMAL1 may be associated with the progression of periodontitis and provides a new perspective on the treatment of periodontitis." (PMID 36613816, 2022). "Given that OS may be a critical pathogenic factor in periodontitis, we next explored the role of BMAL1 in regulating the redox status of periodontal tissues." (PMID 36613816, 2022). "GSDMD-mediated pyroptosis accelerated periodontitis progression, whereas downregulated BMAL1 under circadian disruption further aggravated periodontal destruction by increasing GSDMD activity." (PMID 40000642, 2025). "The extent of bone resorption in the Bmal1- periodontitis group was also significantly higher than in the Bmal1- control group (p<0.001)." (PMID 40008712, 2025). "Knockout of Bmal1 can activate the NF-κB pathway and the expression of downstream inflammatory factors, exacerbating the severity of periodontitis in mice." (PMID 40919224, 2025). "The TRAP stain showed similar result considering the osteoclasts activation that the osteoclasts significantly increased in the Bmal1- periodontitis group." (PMID 40008712, 2025). "In contrast, bone resorption was observed in the buccal alveolar bone in both the wild-type and Bmal1- periodontitis groups but was more pronounced in the Bmal1- group." (PMID 40008712, 2025). "Tnfa expression increased in the Bmal1- with periodontitis group compared with Bmal1+/+ with periodontitis group." (PMID 40008712, 2025). "We investigated the effect of brain and muscle Arnt-like protein-1 (BMAL1) on the NF-κB pathway and downstream inflammatory factors on periodontitis." (PMID 40008712, 2025). "The ELISA results showed the NF-κB signaling related inflammatory cytokines such as TNFa, IL-1β, and IL-6 increased in the Bmal1- periodontitis group." (PMID 40008712, 2025). "The results highlight the protective role of Bmal1 in periodontitis and suggest its potential link to the circadian clock's influence on the disease." (PMID 40008712, 2025). "We observed no noticeable alveolar bone resorption in the Bmal1- control and wild-type groups (i.e., Bmal1+/+ control group), whereas resorption was observed in the two periodontitis groups." (PMID 40008712, 2025). "Taken together, these results indicated that restoring the level of BMAL1 alleviates circadian disruption-aggravated periodontitis via lessening GSDMD-mediated pyroptosis." (PMID 40000642, 2025). "The expression of p65 in the Bmal1- periodontitis group was higher than in the wild-type periodontitis group, and the number of p65-positive cells increased." (PMID 40008712, 2025). "The periodic BMAL1 expression is perturbed when the circadian rhythm is disrupted, resulting in the dysregulation of fibroblasts pyroptosis and further exacerbating periodontitis progression." (PMID 40000642, 2025). "Our results showed significant downregulation of BMAL1 in the CRD with periodontitis group, significant resorption of alveolar bone, increased osteoclast differentiation, and upregulation of the inflammatory signaling molecule NF-κB." (PMID 36613816, 2022). "The BMAL1 gene regulates the innate immune system, and its disruption mediates the release of pro-inflammatory cytokines, which are involved in periodontitis, an inflammatory disorder." (PMID 36366382, 2022). "We used a modified multi-platform approach (MMPM) to induce circadian rhythm disturbances in rats to investigate the role of BMAL1 in periodontitis." (PMID 36613816, 2022).
periodontitis (continued). "To further examine the molecular signaling mechanisms involved in CRD exacerbating periodontitis, we found that BMAL1 has been reported to have a crucial function in regulating intracellular redox status." (PMID 36613816, 2022). "Although there is evidence for the involvement of BMAL1 in periodontitis, its molecular mechanisms in periodontitis are poorly understood." (PMID 36613816, 2022). "Bone resorption in the Bmal1- periodontitis group was significantly greater than that in the wild-type periodontitis group (p<0.01), suggesting the degree of vertical bone resorption in Bmal1- mice during periodontitis was higher than in wild-type mice." (PMID 40008712, 2025). "Evidence from animal studies suggests that circadian rhythm disruption contributes to the onset and progression of periodontitis by modulating the expression of circadian key genes such as BMAL1, thereby affecting oxidative stress, inflammation, and apoptosis in periodontal tissues." (PMID 40672423, 2025). "We hypothesized circadian clock genes, including Bmal1, may be involved in the occurrence and development of periodontitis." (PMID 40008712, 2025). "In conclusion, we validated the vital role of Bmal1 in the development of periodontitis and demonstrated Bmal1 knockout may promote bone destruction and inflammation during periodontitis through the NF-κB pathway." (PMID 40008712, 2025). "Therefore, we established a periodontitis model of Bmal1-mice to explore the regulatory effect of Bmal1 on the NF-κB pathway and its downstream inflammatory factors in the progression of periodontitis." (PMID 40008712, 2025). "In this study, Bmal1 homozygous knockout and periodontitis mouse models were established." (PMID 40008712, 2025). "Furthermore, the expression of p65 in the periodontal tissues of the Bmal1- periodontitis group was higher than the wild-type periodontitis group." (PMID 40008712, 2025). "Quantitative analysis of the average fluorescence intensity and p65-positive cell proportion showed the average optical density and intracellular fluorescence intensity were enhanced in the Bmal1- periodontitis group and the ratio of p65-positive cells increased." (PMID 40008712, 2025). "Moreover, alveolar bone resorption in the Bmal1- periodontitis group was higher than in the wild-type periodontitis group (p<0.05)." (PMID 40008712, 2025). "Other than ACE2, BMAL1, CD147, FURIN, and TMPRSS2, more genes, including CD26(DPP4), IFITM3, HLA, ABO, SLC6A20, GSTT1-M1, and DBP, have also been implicated in SARS-CoV-2 and periodontitis." (PMID 36366382, 2022). "The results also revealed the bone volume/total volume (BV/TV) ratio in the Bmal1- control group was lower than in the wild-type group (p<0.01); similarly, the BV/TV ratio was significantly decreased in the Bmal1- periodontitis group compared with that in the wild-type periodontitis group (p<0.001)." (PMID 40008712, 2025). "Therefore, this study aimed to investigate the role played by BMAL1 in periodontitis." (PMID 36613816, 2022). "Therefore, this study aimed to investigate the role of BMAL1 in periodontitis." (PMID 36613816, 2022). "Therefore, the downregulation of ACE2, CD147, FURIN, and TMPRSS2 genes and the upregulation of BMAL1 may offer a therapeutic strategy against COVID-19 and periodontitis." (PMID 36366382, 2022). "However, in the present study, the role of BMAL1 in the progression of periodontitis was only preliminarily investigated by constructing a circadian rhythm disorder model, and our findings can be further validated in the future using a genetically defective animal model." (PMID 36613816, 2022). "Collectively, the study indicates that BMAL1 may have a crucial role in periodontitis development." (PMID 36613816, 2022). "Consequently, BMAL1 may be a key target to alleviate periodontitis by reducing the inflammatory response." (PMID 36613816, 2022).
periodontitis (continued). "And restoring the level of BMAL1 by circadian recovery and SR8278 injection alleviated simulated shift work-exacerbated periodontitis via lessening GSDMD-mediated pyroptosis." (PMID 40000642, 2025). "Therefore, clock-related BMAL1 may be an important target in treating periodontitis." (PMID 36613816, 2022). "Furthermore, the Bax and Caspase3 expression levels were upregulated, and the amounts of TUNEL-positive cells were raised in the periodontal tissues of the CRD-P group, suggesting that CRD may exacerbate periodontitis by increasing apoptosis levels through the regulation of BMAL1." (PMID 36613816, 2022). "In the present study, five genes were envisaged where BMAL1 is found to be downregulated, and ACE2, CD147, FURIN, and TMPRSS1 are upregulated in periodontitis conditions and the SARS-CoV-2 infection." (PMID 36366382, 2022). "Furthermore, restoring normal circadian rhythm and using SR8278 activates the expressions of BMAL1 and inhibits GSDMD-mediated pyroptosis, thereby ameliorating circadian disruption-accelerated periodontitis progression." (PMID 40000642, 2025). "Although our study provides new insights into the mechanisms of circadian disruption-deteriorated periodontitis and the previously undiscovered roles of BMAL1 in GSDMD-mediated pyroptosis, some limitations should be noted." (PMID 40000642, 2025). "Collectively, our study suggests that BMAL1 is a key regulator in periodontitis exacerbated by CRD and that CRD may lead to the downregulation of BMAL1, thereby exacerbating oxidative stress and apoptosis in periodontal tissues." (PMID 36613816, 2022). "Therefore ACE2, TMPRSS2, FURIN, CD147, and BMAL1 are the crossroads between SARS-CoV-2 and Periodontitis genes." (PMID 36366382, 2022). "Moreover, we revealed that BMAL1/GSDMD signaling acts as a coordinator of shift work-related circadian disruption and periodontitis progression, providing a potential guidance for the development of intervention strategies targeting circadian clock against periodontitis." (PMID 40000642, 2025).
ischemia (7 papers, 2018 to 2025). A hypoperfusion of the BLOOD through an organ or tissue caused by a PATHOLOGIC CONSTRICTION or obstruction of its BLOOD VESSELS, or an absence of BLOOD CIRCULATION. "For instance, in mouse models of cerebral ischemia-reperfusion, Bmal1 overexpression effectively reduces cerebral edema, diminishes infarct volume, and decreases neuronal apoptosis induced by ischemia." (PMID 40527853, 2025). "A hindlimb ischemia model performed in wild-type and Bmal1−/− mice confirmed that Bmal1 disruption would lead to impaired angiogenesis." (PMID 34447794, 2021). "In Bmal1−/− mice, the volume of densely packed microglia following ischemia was significantly larger in females as compared to males seven days after PT." (PMID 30314381, 2018). "Therefore, ventricular electrophysiological properties before MI were stabilized, and ischemia-induced VAs were suppressed by Bmal1 knockdown-mediated decline of LSG neural activity." (PMID 36247430, 2022). "Therefore, we concluded that BMAL1 contributes to revascularization after ischemia in mice and CLI patients by promoting angiogenesis." (PMID 34447794, 2021). "In this context, we have also examined the relationship between Bmal1, melatonin and PI3K signaling pathway using in vivo and in vitro ischemia." (PMID 31836786, 2019).
ischemic stroke (7 papers, 2023 to 2025). A stroke disorder caused by obstruction of blood flow to the brain, due to thrombotic (local blood clot formation) or embolic (due to a blood clot or other material traveling from another site) event. "Similarly, other groups have demonstrated that deletion of Bmal1 in microglia appears to reduce inflammatory activation and reduce damage caused by ischemic stroke." (PMID 38032732, 2024). "Our results showed higher MDA, IL-6, and TNF-α levels, and lower SOD, SIRT1, and BMAL1 levels in ischaemic stroke patients compared to control patients (P < 0.05)." (PMID 38245621, 2024). "In mouse models of ischemic stroke (Table A1) created at four different time points, ischemia induced at midnight was characterized by increased expression of BMAL1, PER1, CLOCK circadian proteins, AKT, and ERK-1/2 cell survival kinases compared with ischemia induced at other time points." (PMID 41440117, 2025). "Animal studies have shown that BMAL1 is also involved in oxidative stress in ischaemic stroke." (PMID 38245621, 2024). "However, the impact of BMAL1 on oxidative stress and inflammation in the progression of ischaemic stroke remains unclear." (PMID 38245621, 2024). "Certain subgroups of ischemic stroke patients had the lowest expression levels of SOD, BMAL1, and SIRT1, whereas other subgroups had the highest levels of MDA, IL-6, and TNF-α." (PMID 41567643, 2025). "Within 4.5 h after ischemic stroke onset, compared with those in the control group, the relative protein levels of SIRT1 and BMAL1 in the peripheral blood decreased, whereas the levels of oxidative stress and inflammation markers increased." (PMID 41440117, 2025). "When comparing the relative expression levels of BMAL1 and SIRT1 proteins among the four subgroups, a significant decrease in BMAL1 and SIRT1 expression levels was found in patients with ischaemic stroke onset from subgroup 2 (6:00 to 11:59)." (PMID 38245621, 2024). "Among the four subgroups, the content of MDA, IL-6, and TNF-α was highest in patients with ischaemic stroke onset from subgroup 2 (06:00–11:59), while the expression levels of SOD, BMAL1, and SIRT1 were lowest in patients with ischaemic stroke in subgroup 2." (PMID 38245621, 2024). "A significant reduction in the expression levels of basic helix–loop–helix ARNT Like 1 (BMAL1) and the transcription regulator of circadian clock genes (SIRT1) was also demonstrated in patients with ischemic stroke from group 2." (PMID 39334896, 2024). "This study found a downward trend in BMAL1 and SIRT1 expression along with increased activation of oxidative stress (MDA) and inflammatory factors (IL-6, TNF-α) in patients with early-onset ischemic stroke." (PMID 38245621, 2024). "Moreover, comparisons of BMAL1 and SIRT1 levels across four different time subgroups in patients (00:00–05:59, 06:00–11:59, 12:00–17:59, and 18:00–23:59) revealed that expression levels were lowest in patients with ischemic stroke onset at 6:00–11:59." (PMID 41440117, 2025). "Pearson correlation analysis showed a moderate positive correlation between BMAL1 and SIRT1, as well as between BMAL1 and SOD (r = 0.69; r = 0.73, respectively), indicating that SIRT1-BMAL1 may contribute to the early onset of ischemic stroke by regulating oxidative stress." (PMID 39334896, 2024).
lymphoma (7 papers, 2010 to 2019). A malignant (clonal) proliferation of B- lymphocytes or T- lymphocytes which involves the lymph nodes, bone marrow and/or extranodal sites. "Previous studies demonstrated that mutation or knock out of clock genes Per2, Cry1/Cry2 or Bmal1 also accelerated the development of lymphomas following whole body exposure to γ radiations." (PMID 27494874, 2016). "Here, a more detailed analysis of the regulation of DNA methylation of BMAL1 proceeded in RPMI8402 lymphoma cells." (PMID 28487473, 2017). "About 8% of irradiated Bmal1−/− mice also developed lymphoma despite an average lifespan of 27 weeks due to a further accelerated rate of aging." (PMID 20539819, 2010). "Consistent with our observation in U2OS cells, expression of both clock genes correlated inversely with MYC levels in human lymphoma (Pearson coefficient −0.61 and −0.37 for BMAL1 and CLOCK, respectively; n=102), whereas MYC-activated genes such as NCL and NCLN showed a positive correlation." (PMID 27339797, 2016). "Restoration of BMAL1 and CLOCK circadian oscillation in lymphoma cells by using a PERK (protein kinase RNA-like endoplasmic reticulum kinase) inhibitor reduced tumor cell survival." (PMID 33089179, 2019). "Encouraged by the inverse correlation of MYC with BMAL1 and CLOCK expression in U2OS cells, we assessed expression of these genes in human lymphoma by analysing RNA-seq data of 102 patient samples." (PMID 27339797, 2016). "The inverse correlation of BMAL1 versus MYC expression levels in human lymphomas and the absence of a positive correlation of MYC with circadian E-box genes support this hypothesis." (PMID 27339797, 2016).
malignant pleural mesothelioma (7 papers, 2017 to 2023). A malignant neoplasm that arises from mesothelial cells in the pleura and shows a diffuse growth pattern. "By contrast, BMAL1 depletion inhibits the cell cycle in malignant pleural mesothelioma with the downregulation of Wee1, cyclin B, and p21 and the upregulation of cyclin E." (PMID 32231148, 2020). "In contrast, over-expression of BMAL1 contributes to the aggressiveness of malignant pleural mesothelioma, with knockdown of BMAL1 suppressing cell proliferation." (PMID 30348208, 2018). "For instance, an increase in BMAL1 expression was found in malignant pleural mesothelioma." (PMID 33194597, 2020). "BMAL1 is likely to play a role in cancer prevention in malignant pleural mesothelioma." (PMID 31346317, 2019). "Similarly, Bmal1 knockdown suppressed the proliferation of malignant pleural mesothelioma." (PMID 37504857, 2023).
schizophrenia (7 papers, 2017 to 2025). A major psychotic disorder characterized by abnormalities in the perception or expression of reality. "The impaired cognitive function in novelty detection suggests BMAL1 deficiency had triggered a schizophrenia-like symptom." (PMID 34691834, 2019). "However, HAL action dysregulated other genes also associated with schizophrenia in humans, such as Col6a3, Slc22a8, and Bmal1." (PMID 39825014, 2025). "HAL and KARI201 antipsychotic effects were associated with targeting expression of other schizophrenia associated genes like Col6a3, Slc22a8, and Bmal1, or Nr2f6a, respectively, but none affecting expression of sphingolipid regulating genes." (PMID 39825014, 2025). "In addition, the first primate model of deficiency for a core rhythm gene was generated by CRISPR/Cas9-mediated knockout of Bmal1 in macaque, which resulted in schizophrenia-like symptoms, further supporting a possible role of Bmal1 in neurological disorders." (PMID 36593479, 2023).
acute pancreatitis (6 papers, 2023 to 2025). An acute inflammatory process that leads to necrosis of the pancreatic parenchyma. "The mice with specific deletion of pancreatic ARNTL/BMAL1 a are more susceptible to developing acute pancreatitis, and this pancreatic damage is inhibited by the administration of the ferroptosis inhibitor liproxstatin-1." (PMID 39587094, 2024). "In acute pancreatitis experiments, it was determined that Bmal-1 plays a protective role by mitigating inflammatory injury through the inhibition of ferroptosis-mediated HMGB1 release." (PMID 39296207, 2024). "The circadian transcription factor ARNTL (also known as BMAL1) prevents experimental acute pancreatitis by blocking the ferroptosis-mediated release of HMGB1 (a sterile inflammatory mediator)." (PMID 39769097, 2024).
arthropathy (6 papers, 2008 to 2024). Any disorder of the joints. "In agreement with functional redundancy of NPAS2 and CLOCK, only double deficiency of CLOCK and NPAS2 in mice results in arthropathy (E.A. Yu and D.R. Weaver, personal communication) similar to arthropathy developed upon BMAL1 deficiency CLOCK is the major interacting partner of BMAL1." (PMID 21149897, 2010). "Therefore, to determine the impact of FLS Bmal1 deletion on established joint disease, our subsequent analyses compare joints from symptomatic CIA mice with severe disease (paw score of ≥ 3)." (PMID 38981514, 2024). "Muscle-rescued Bmal1−/− mice exhibit improvement of body weight, activity, and longevity but not of arthropathy." (PMID 25525750, 2014).